JMJD6 (jumonji domain containing 6, arginine demethylase and lysine hydroxylase)
Diseases named in the same sentence as JMJD6 in open-access papers (continued):
Sharing a sentence is not in itself a finding about the gene and the disease.
neuroblastoma (continued). "Here, we demonstrate that jumonji domain containing 6, arginine demethylase, and lysine hydroxylase, JMJD6, acts as a hub connecting splicing and metabolism in MYC-driven human neuroblastoma." (PMID 38488852, 2024). "(F) Spearman correlation analysis of JMJD6 and GAC/KGA expression levels in two neuroblastoma cohorts GSE45547 (left) and GSE120572 (right)." (PMID 38488852, 2024). "We show that JMJD6 controls the alternative splicing of KGA and GAC, and, consequently, impacts the central carbon metabolism in neuroblastoma." (PMID 38488852, 2024). "However, our unbiased identification of the JMJD6 interactome only identified a subset of proteins involved in mRNA splicing and protein translation in neuroblastoma cells, suggesting that JMD6 may predominantly regulate protein homeostasis to facilitate MYC-mediated transformation." (PMID 38488852, 2024). "Importantly, we have confirmed that JMJD6 protein forms a complex with BRD4 protein in neuroblastoma cells, that JMJD6 protein directly binds to N-Myc protein at the Myc Box II region, and that the majority of super-enhancers, typical enhancers, and promoters bound by JMJD6 are also bound by N-Myc." (PMID 31346162, 2019). "Suppression of JMJD6 resulted in decreased E2F2, N-Myc, and c-Myc gene expression, reduced neuroblastoma cell proliferation, induction of apoptosis in vitro, and inhibition of tumor growth in vivo." (PMID 31346162, 2019). "The data demonstrate that JMJD6 is important for E2F2 and Myc expression, neuroblastoma tumor progression, and mouse survival in vivo." (PMID 31346162, 2019). "Immunoblot analysis showed that the anti-BRD4 and anti-JMJD6 antibodies efficiently immunoprecipitated both BRD4 and JMJD6 proteins, suggesting that JMJD6 forms a protein complex with BRD4 in neuroblastoma cells." (PMID 31346162, 2019). "We previously found that JMJD6 is essential for the survival of neuroblastoma cells (including MYCN-amplified and MYC-overexpressed cells), which was further validated by an independent study, indicating that neuroblastoma has JMJD6 dependency." (PMID 38488852, 2024). "As JMJD6 regulates Myc and E2F2 expression, we examined whether JMJD6 modulates neuroblastoma cell proliferation, survival, and clonogenic capacity." (PMID 31346162, 2019). "The data showed that JMJD6 co-dependency genes were significantly and positively correlated with spliceosome/mRNA splicing (i.e. RBM39, SF3B1), ubiquitin-mediated proteolysis and endocytosis and a number of 17q25 genes, which mirrored the pathway network of 17q essential genes in neuroblastoma." (PMID 38488852, 2024). "Notably, JMJD6 controls the alternative splicing of two isoforms of glutaminase (GLS), namely kidney-type glutaminase (KGA) and glutaminase C (GAC), which are rate-limiting enzymes of glutaminolysis in the central carbon metabolism in neuroblastoma." (PMID 38488852, 2024). "Furthermore, high levels of JMJD6 mRNA expression in the 405 MYCN-non-amplified and the 66 MYCN-amplified neuroblastoma tissues were also positively associated with poor patient overall survival in the large Oberthuer dataset." (PMID 31346162, 2019). "Indeed, JMJD6 was positively correlated with GAC and negatively correlated with KGA in two independent neuroblastoma cohorts, supporting the hypothesis that JMJD6 is required to maintain the high ratio of GAC/KGA in cancer cells by controlling their alternative splicing." (PMID 38488852, 2024). "We therefore examined whether N-Myc and c-Myc modulated JMJD6 gene expression in CHP134 (chromosome 17q21-ter/JMJD6 gained and MYCN amplified) and SK-N-AS (chromosome 17q21-ter/JMJD6 gained and MYCN-non-amplified) neuroblastoma cells." (PMID 31346162, 2019).
lung carcinoma (8 papers, 2018 to 2025). "At the same time, a subgroup of cells that highly express CD44 and CD133, two common surface markers for lung cancer stem cells, was selected with flow cytometry assays and detected for JMJD6 positivity." (PMID 41320721, 2025). "Among the overlapping target genes, EHF, the expression of which is correlated with increased metastasis of lung cancer cells is by far one of the most downregulated overlapping targets of JMJD6." (PMID 41320721, 2025). "To verify that JMJD6 depletion inhibits murine cell motility, we conducted transwell assays using mouse lung cancer cell lines LL/2 and CMT-64." (PMID 41320721, 2025). "To confirm that EHF is the downstream effector of JMJD6 in radiation-induced lung-cancer metastasis, we transfected shJMJD6 A549 cells with an EHF-overexpression plasmid and monitored cell migration." (PMID 41320721, 2025). "These rescue data demonstrated that JMJD6 promoted lung cancer metastasis predominantly through transcriptional up-regulation of EHF." (PMID 41320721, 2025). "Recently, multiple studies have shown that JMJD6 was regulated by miRNAs (Mir-770, Mir-519D-3p, Mir-106a-5p) in lung cancer." (PMID 35359945, 2022). "JMJD6 is one of the most frequently altered genes in lung cancer, and plays a role in promoting lung cancer." (PMID 35359945, 2022). "However, apoptosis is enhanced in cisplatin (DDP)-resistant A549 (A549/DDP) cells via connecting JMJD6 per se, and it suggests MiR-106a-5p and JMJD6 as a potential biomarker in lung cancer." (PMID 37986065, 2023). "Similarly, another research showed that there was negative regulation between JMJD6 and Mir-106a-5p in cisplatin-resistant lung cancer cells, inhibition of JMJD6 reduced the proliferation, invasion and migration capacity, and thus alleviated the resistance of cisplatin." (PMID 35359945, 2022). "Notably, targeting JMJD6 may provide additional ways to treat lung cancer, since suppressing JMJD6 via acetylating its upstream transcriptional factor HOXB9 resulted in a decrease in tumor growth and migration in xenograft models." (PMID 30002791, 2018). "Knockdown of JMJD6 in A549 cells reduced the metastasis incidence of lung cancer regardless of IR treatment." (PMID 41320721, 2025). "JMJD6 and KDM4A might serve as biomarkers for lung cancer although further mechanistic investigations were necessary." (PMID 30002791, 2018). "To identify the role of JMJD6 expression in the antitumor effect of TAM-like THP-1 cells, we collected conditioned medium (CM) of Mock, sh-Scr or sh-J6 TAM-like THP-1 cells, and resuspended human lung cancer H460 cells with the CM, which was then inoculated subcutaneously in NOD-SCID mice." (PMID 37567973, 2023).
liver cancer (6 papers, 2017 to 2024). An epithelial or non-epithelial malignant neoplasm that arises from the liver. "JMJD6 was amplified across multiple types of adult cancers such as breast and liver cancer, and correlated with worse relapse-free survival." (PMID 38488852, 2024). "Further, the expression of HOTAIR was regulated by JMJD6–BRD4 complex, and the JMJD6 inhibitor contributed to the radiosensitivity of liver cancer cells by suppressing the expression of HOTAIR and ERK2 (MAPK1)." (PMID 37880710, 2023). "The compound WL12 has been shown to inhibit JMJD6 enzymatic activity, as well as the JMJD6-dependent proliferation of cervical and liver cancer cells." (PMID 37218871, 2023). "Further, through cellular tumorigenicity in nude mice, we explored whether JMJD6-mediated radioresistance in liver cancer cells was related to the regulation of ERK2 (MAPK1) by the HOTAIR-LSD1 axis." (PMID 37880710, 2023). "BRD4 and JMJD6 were highly expressed in liver cancer tissues." (PMID 37880710, 2023). "Additionally, JMJD6 has been indicated to participate in the development of multiple cancers, including liver cancer, and the enzymatic activity of JMJD6 was pivotal for cancer progression." (PMID 37880710, 2023). "Collectively, JMJD6 inhibitor SKLB325 could effectively attenuate radioresistance of liver cancer cells by reducing LCSC stemness in vivo and in vitro." (PMID 37880710, 2023). "JMJD6 may be involved in carcinogenesis and poor prognosis of liver cancer." (PMID 35359945, 2022). "For verification, we first detected the expression of JMJD6 and BRD4 in liver cancer tissues and adjacent normal tissues by RT-qPCR." (PMID 37880710, 2023).
viral infection (6 papers, 2014 to 2026). "Meanwhile, the IRF3 polyubiquitination was examined using JMJD6-deficient cells and JMJD6-rescued cells upon virus infection with MG132 treatment." (PMID 33684176, 2021). "IRF3 stability was examined using JMJD6-deficient and JMJD6-rescued cells upon virus infection." (PMID 33684176, 2021). "The results presented here indicate that increased expression of JMJD6 suppresses the innate antiviral responses and promotes viral replication, which may partly explain why cancer cells are more susceptible to viral infection since abundant JMJD6 expression in cancer cells." (PMID 33684176, 2021). "When JMJD6 was reconstituted into KO-JMJD6 cells, JMJD6 rescued viral infection compared with KO-JMJD6 cells." (PMID 33684176, 2021). "Furthermore, we identified METTL23 as a nuclear interactor of JMJD6 upon viral infection, revealing a cooperative role between these proteins in facilitating immune evasion." (PMID 42053297, 2026). "Moreover, RNF5 and IRF3 showed significant translocation from the cytoplasm into the nucleus upon viral infection, which indicates that JMJD6 recruits RNF5 and IRF3 together in the nucleus upon viral infection." (PMID 33684176, 2021). "Genetic inactivation of JMJD6 in cells increases IFN-I production to suppress viral infection." (PMID 33684176, 2021). "These indicate that JMJD6 catches RNF5 to degrades IRF3 in the nucleus upon viral infection." (PMID 33684176, 2021).
breast tumors (5 papers, 2012 to 2022). "Of note, co-expression of high levels of JMJD6 and c-Myc is associated with poor prognosis for patients harboring ERα-positive breast tumors." (PMID 27556302, 2016). "In breast cancer, a high level of JMJD6 mRNA expression was linked with tumors with poor outcomes, which was confirmed at the protein level, after analyzing 133 breast tumors." (PMID 27556302, 2016). "Together, these data implicate JMJD6 function in breast tumor progression and suggest a diagnostic role for JMJD6 in predicting patient outcomes." (PMID 22621393, 2012). "The analysis of JMJD6 expression in a cohort of breast tumour samples indicates that JMJD6 was highly expressed in aggressive breast tumours." (PMID 25951181, 2015). "As shown, JMJD6 was present predominantly in the nuclei of breast tumor cells, with increased staining evident in higher grades of breast tumors." (PMID 22621393, 2012). "To study the distribution of JMJD6 protein levels, we immunohistochemically (IHC) stained an 81-breast tumor tissue array by using a JMJD6-specific antibody." (PMID 22621393, 2012). "For example, JMJD6 demethylates ERα, suggesting that the demethylase activity of JMJD6 could disturb non-genomic estrogen signaling, a pathway activated in aggressive breast tumors." (PMID 27556302, 2016). "We could hypothesise that in breast tumours, JMJD6 could lose its enzymatic activity for several reasons." (PMID 25951181, 2015). "JMJD6 expression in 133 breast tumour samples revealed that a high expression of JMJD6 correlated with deleterious factors: younger patients, more pre-menopausal women, patients with higher SBR grade and more non luminal A tumours and could therefore be marker of bad prognosis." (PMID 25951181, 2015). "Moreover, high expression of JMJD6 was associated with non-luminal A breast tumours (54.1% versus 27.5% of patients with a low expression of JMJD6, p = 0.002)." (PMID 25951181, 2015). "However, the study of JMJD6 expression in a cohort of breast tumours indicated that JMJD6 may instead be a marker of poor prognosis." (PMID 25951181, 2015). "However, the analysis of JMJD6 expression in breast tumour specimens does not give any information about its activity." (PMID 25951181, 2015).
glioma (5 papers, 2020 to 2024). A benign or malignant brain and spinal cord tumor that arises from glial cells (astrocytes, oligodendrocytes, ependymal cells). "A recent study showed that JMJD6 interacted with n-Myc and BRD4 to form protein complexes that induce the expression of E2F2 and Myc, which increased glioma carcinogenic risk." (PMID 35359945, 2022). "Levels of JMJD6 mRNA and protein are significantly elevated in human glioma tissues, and are increased with tumour grade." (PMID 31961032, 2020). "Moreover, enhancer-mediated transcriptional pause-release is also one of the reasons for JMJD6-induced tumorigenesis of glioma." (PMID 35359945, 2022). "Furthermore, expression of JMJD6 was shown to increase with glioma grade and inhibiting JMJD6 extended survival of the glioma-bearing mice." (PMID 34207158, 2021).
Autoimmunity (4 papers, 2014 to 2022). The occurrence of an immune reaction against the organism's own cells or tissues. "Here the authors show that Jmjd6 directs splicing of a central tolerance regulator Aire in medullary thymic epithelial cells, and that Jmjd6 deficiency leads to loss of Aire and multi-organ autoimmunity in mice." (PMID 26531897, 2015). "As a result, the expression of Aire protein was markedly reduced in Jmjd6-deficient (Jmjd6−/−) mTECs, and T-cells generated in such thymic microenvironments caused multi-organ autoimmunity in mice." (PMID 26531897, 2015). "In addition, by grafting Jmjd6−/− thymic stroma into athymic C57BL/6 nude mice, we have shown that T-cells selected to mature in Jmjd6−/− thymic microenvironments caused multi-organ autoimmunity." (PMID 26531897, 2015). "The lack of functional Aire protein expression in Jmjd6-/- mTECs generates multi-organ autoimmunity in nude mice that are reconstituted with thymic Jmjd6 knockout grafts." (PMID 28360925, 2017). "Although Jmjd6 deficiency does not affect abundance of Aire transcript, the intron 2 of Aire gene is not effectively spliced out in the absence of Jmjd6, resulting in marked reduction of mature Aire protein in mTECs and spontaneous development of multi-organ autoimmunity in mice." (PMID 26531897, 2015).
colorectal cancer (4 papers, 2016 to 2025). A primary or metastatic malignant neoplasm that affects the colon or rectum. "Previous research has suggested the association between JMJD6 and many diseases, especially s-JMJD6-Ab and colorectal cancer." (PMID 38732153, 2024).
colon adenocarcinoma (3 papers, 2014 to 2020). "Immunohistochemical staining showed that compared to normal tissues, JMJD6 protein was significantly up-regulated in colon adenocarcinomas (paired-samples t test, p = 0.001)." (PMID 24667498, 2014). "JMJD6 protein is significantly increased in colon adenocarcinomas." (PMID 31961032, 2020). "We found significant positive correlations between high JMJD6 expression and poor histological grade, advanced TNM stage, and shorter survival time in colon adenocarcinomas." (PMID 24667498, 2014).
hepatocellular carcinoma (3 papers, 2022 to 2025). A malignant tumor that arises from hepatocytes. "JMJD6 also expedites the proliferation and controls the cell cycle of hepatocellular carcinoma cells by directly targeting CDK4 and modulating histone modifications on the CDK4 promoter." (PMID 35359945, 2022). "Furthermore, c-Jun-mediated JMJD6 repair enhances radioresistance in hepatocellular carcinoma through the IL-4-activated ERK pathway." (PMID 40092686, 2025). "Intriguingly, a positive correlation between cell cycle regulatory protein CDK4 and JMJD6 expression was identified, and mechanistic analysis indicated JMJD6 enhanced CDK4 expression in hepatocellular carcinoma by directly binding to its promoter." (PMID 38166895, 2024).
lymph node metastasis (3 papers, 2017 to 2023). "High level of JMJD6 expression is correlated with increased invasiveness, poor differentiation, lymph node metastases and advanced stage." (PMID 31961032, 2020).
oral squamous cell carcinoma (3 papers, 2020 to 2024). "Previously study have shown that JMJD6 expression was higher in human oral squamous cell carcinoma by inducing interleukin 4 transcription and binding to its promoter region." (PMID 37488513, 2023). "Immunohistochemical staining of 18 normal human oral epithelia samples and 16 oral squamous cell carcinoma samples showed that the expression level of JMJD6 is higher in carcinoma tissues." (PMID 31961032, 2020). "In oral squamous cell carcinoma cases, the strong JMJD6 staining rate is 69%, while 89% normal human oral epithelia cases show weak JMJD6 staining." (PMID 31961032, 2020).
renal cell carcinoma (3 papers, 2021 to 2022). "JMJD6 is highly expressed in oral squamous cell carcinoma (OSCC), head and neck squamous cell carcinoma (HNSCC), esophageal squamous cell carcinoma (ESCC), osteosarcoma, acute myeloid leukemia (AML), and renal cell carcinoma (RCC)." (PMID 35359945, 2022).
triple-negative breast carcinoma (3 papers, 2020 to 2022). An invasive breast carcinoma which is negative for expression of estrogen receptor (ER), progesterone receptor (PR), and human epidermal growth factor receptor 2 (HER2). "Recently, an additional function for JMJD6 as a tyrosine kinase targeting the Y39 tyrosine of the histone variant H2A.X has been reported in triple negative breast cancer cell lines overexpressing JMJD6." (PMID 32598339, 2020). "For example, JMJD6 not only had intrinsic tyrosine kinase activity but also phosphorylated Y39 of histone H2A.X (H2A.XY39ph) in triple negative breast cancer (TNBC) cells, then autophagy regulated by JMJD6- H2A.XY39ph axis promoted cell growth." (PMID 35359945, 2022). "In clinical samples, JMJD6 and EZH2 expression significantly correlated in both normal and tumor samples, however the strongest correlation was observed in triple-negative breast cancer (TNBC) subtype." (PMID 33246425, 2020).
acute myeloid leukemia (2 papers, 2022 to 2023). Acute myeloid leukemia (AML) is a group of neoplasms arising from precursor cells committed to the myeloid cell-line differentiation. "This ET domain interacts with a variety of cellular proteins such as histone-lysine N-methyltransferase (NSD3) and Jumonji domain-containing 6 (JMJD6), whose interactions are implicated in acute myeloid leukemia (AML) and various solid tumors, respectively." (PMID 37049806, 2023).
anaemia (2 papers, 2025). "Given the severe phenotypes observed following JMJD6 knockout, this is of particular importance with respect to clinically-used inhibitors of the PHDs for long-term treatment of anaemia." (PMID 40046450, 2025).